ALB (albumin)
Diseases named in the same sentence as ALB in open-access papers (continued):
Sharing a sentence is not in itself a finding about the gene and the disease.
liver cirrhosis (continued). "This review discusses the potential benefits of albumin infusion for renal function in patients with cirrhosis of the liver." (PMID 26136776, 2015). "The concentrations of glucose (p<0.05), total proteins (p<0.01), albumin (p<0.01), A/G ratio (p<0.05), and fibrinogen (p<0.05) were significantly lower in the liver cirrhosis group compared to the control group." (PMID 27047120, 2015). "This patient with liver de-compensation had marked jaundice (total bilirubin level: 136 umol/L), liver cirrhosis with severe splenomegaly and thrombocytopenia, but the albumin level was normal." (PMID 24475083, 2014). "Low serum albumin level, liver cirrhosis, perioperative transfusion, perioperative bleeding, perioperative morbidity, multiple tumors, and poor histologic grade were independent adverse prognostic factors for patients with tumors larger than 3 cm." (PMID 24961934, 2014). "In the current study, preoperative serum albumin level and platelet count, which reflect liver function and severity of liver cirrhosis, were independent prognostic factors for overall survival after liver resection." (PMID 24961934, 2014). "Age >50 years, liver cirrhosis, bilirubin >1.1 mg/dl (P < 0.01, each), platelets <100,000/μl (P = 0.01), ASAT >100 U/l (P = 0.03) and albumin ≤35 g/l (P = 0.04) at baseline were associated with occurence of a SAE." (PMID 24884400, 2014). "Forty patients with liver cirrhosis, low serum albumin, and low zinc levels were randomized to receive either branched-chain amino acids alone or a combination of branched-chain amino acids and zinc supplements." (PMID 23742732, 2013). "It is well known that albumin and bilirubin are key components of the Child-Turcotte-Pugh score that clinicians use to assess decompensated liver cirrhosis." (PMID 23056462, 2012). "Our study demonstrated the prognostic values of albumin levels in head and neck cancer patient with liver cirrhosis." (PMID 23285146, 2012). "During the development of liver cirrhosis bilirubin rose markedly, whereas there was a significant decrease of plasma albumin." (PMID 21423778, 2011). "Recently, a novel trial of intravenous transplantion of autologous bone marrow-derived stromal cells (BMSCs) in patients with liver cirrhosis reported improved serum albumin and total protein levels." (PMID 19134049, 2008). "Data of patients with liver cirrhosis (LC) were collected from the Medical Information Mart for Intensive Care III database to explore whether anion gap (AG) and albumin-adjusted AG (AA-AG) values were associated with outcomes in patients with LC." (PMID 41824872, 2026). "The results showed that age, decompensated liver cirrhosis, PT, LSM, MELD score, and Child–Pugh score were significantly positively associated with the occurrence of complications, whereas WBC, RBC, HGB, PLT, and ALB were negatively correlated." (PMID 40672818, 2025). "Benign liver diseases also often cause damage to liver functions (liver cirrhosis, hepatitis, etc.), which may be the reason for the relatively small differences in levels of TBIL, PLT and ALB among HCC, CCA and benign liver diseases patient cohorts." (PMID 40708828, 2025). "Therefore, improvement in MELD score and Child-Pugh classification and increase in albumin level in liver cirrhosis patients after anticoagulation therapy are important indicators for assessing the effectiveness of treatment." (PMID 39003447, 2024). "Finally, simultaneous RNA FISH to detect Fendrr and immunofluorescence for albumin showed a significant increase of Fendrr in the hepatocytes of liver cirrhosis patients in comparison with the normal control." (PMID 38762176, 2024). "In addition, data gathered from patients with advanced fibrosis or liver cirrhosis caused by ALD, serum albumin, bilirubin, and white blood cell levels are also used to determine the severity of liver injury." (PMID 38542468, 2024). "Many liver-related disorders, such as liver cirrhosis, impact the level and function of albumin." (PMID 38813321, 2024).
liver cirrhosis (continued). "In the subgroup of patients with liver cirrhosis, PC 32:0 was positively related with bilirubin (r = 0.511, p = 0.020), and PC 37:4 (r = 0.545, p = 0.007), 38:6 (r = 0.677, p < 0.001) and PC 40:6 (r = 0.548, p = 0.007) with albumin." (PMID 39125730, 2024). "Elevated albumin levels in patients with liver cirrhosis may indicate that the patient’s liver synthetic function has improved." (PMID 39003447, 2024). "Here, we summarize currently available evidence of the potential benefits of human albumin for the management of multiple liver cirrhosis‐related complications and discuss key challenges for wide application of long‐term albumin administration strategy in Australian clinical practice." (PMID 39301299, 2024). "Importantly, albumin represented a good prognostic factor, being a significant predictor of death in patients with liver cirrhosis." (PMID 37569584, 2023). "So far, there are four albumin-based liver reserve models specifically for liver cirrhosis and HCC." (PMID 37046586, 2023). "Confirming the positive impact of TIPS implantation on muscle indices in patients with liver cirrhosis, we found indications for improved survival and possible indications for altered metabolism with increased albumin levels in patients with increased muscle quantity." (PMID 37816875, 2023). "The serum albumin level is well known for its predictive ability in patients with liver cirrhosis." (PMID 38069310, 2023). "In addition, Child–Pugh B, low albumin, liver cirrhosis, and transcatheter arterial chemoembolization (TACE) after recurrence were factors related to gallstones in patients with primary liver cancer after hepatectomy." (PMID 36936662, 2023). "Although recent studies have investigated the efficacy of albumin in the resuscitation stage of septic patients with liver cirrhosis, it remains unclear whether daily albumin administration can improve outcomes." (PMID 37507790, 2023). "Furthermore, decompensated liver cirrhosis and decreased serum albumin independently affected the progression of cryptococcosis in the CM and PC groups, respectively." (PMID 38115055, 2023). "Therefore, patients with liver cirrhosis or who are malnourished tend to have lower serum albumin levels." (PMID 35672868, 2022). "As critical illness affects the synthesis and degradation of albumin, the pattern of change in serum albumin and the clinical significance may differ in patients with liver cirrhosis or cancer with critical illness." (PMID 35672868, 2022). "Therefore, the current meta-analysis was conducted to determine the impact of IV human albumin in patients with liver cirrhosis and spontaneous bacterial peritonitis (SBP)." (PMID 36721617, 2022). "Therefore, this study aimed to evaluate the effects of rifaximin on the structure of circulating albumin and serum ammonia levels in patients with liver cirrhosis." (PMID 36555935, 2022). "In contrast to AFP, CA19-9 levels ≤ 37 U/mL were significantly associated with higher values of alanine aminotransferase (ALT), AST, serum albumin, Child–Pugh score, and total bilirubin (TBil), as well as with positive hepatitis B surface antigen (HBsAg) and liver cirrhosis." (PMID 36258212, 2022). "Since albumin is only synthesized in the liver, it is a useful indicator of hepatic function, and a decrease in albumin may indicate chronic liver disease or liver cirrhosis." (PMID 36684957, 2022). "The AASL score consisted of age, albumin, sex, and liver cirrhosis." (PMID 34830764, 2021). "In addition to IL values, liver cirrhosis, Child–Pugh grade, baseline albumin (< 36 g/dL), and total bilirubin (≥ 17 μmol/L), and higher mALBI grade (2b &3) values were associated with OS." (PMID 34080071, 2021). "Improved HCC prediction by incorporation of liver function (albumin) into a modified PAGE-B score hereby indicated that unrecognized liver cirrhosis could be responsible for this finding." (PMID 34419018, 2021).
liver cirrhosis (continued). "Patients with decompensated liver cirrhosis have ca. 75% decreased albumin and plasma zinc levels." (PMID 34836265, 2021). "Besides high IL6 and high IL8, liver cirrhosis (p = 0.032), Child–Pugh class B (p = 0.014), albumin < 36 g/L (p = 0.024), total bilirubin ≥ 17 μmol/L (p = 0.009), and higher (2b and 3) mALBI grade (p = 0.007) were associated with worse outcome." (PMID 34080071, 2021). "The components of CU-HCC are age, albumin, liver cirrhosis, bilirubin, and HBV DNA." (PMID 34830764, 2021). "In addition, liver cirrhosis not only decreases the levels of albumin but also leads to pronounced changes in its molecular integrity." (PMID 34836265, 2021). "This leads to the question whether vasoactive molecules such as bile acids could be bound by the administration of fresh albumin in order to compensate for a reduced albumin concentration and its impaired structural integrity in liver cirrhosis." (PMID 34393832, 2021). "In particular, we focus on the major role of chronic inflammatory processes in pathogenesis and progression of liver cirrhosis and how albumin therapy and zinc supplementation may affect these processes." (PMID 34836265, 2021). "Albumin is a substance of interest when dealing with liver cirrhosis patients." (PMID 34492024, 2021). "In the multivariate analysis associated with frailty, for the male participants, only the presence of liver cirrhosis (p = 0.0433) was identified to be significant, while among the female participants, serum albumin (p = 0.0444) and CC (p = 0.0010) were identified to be significant." (PMID 32630551, 2020). "In addition, in patients with liver cirrhosis, BCAA supplementation was associated with a decrease of intramuscular fat mass only in patients with restored plasma albumin." (PMID 33202638, 2020). "Interestingly, the software demonstrated that some of the identified proteins were related to albumin which is the main factor in the management of complications of liver cirrhosis." (PMID 33585012, 2020). "However, that can increase in the case of liver cirrhosis or other severe hepatic impairment patients with decreased albumin production, or drug-induced bilirubin displacement on the albumin binding sites." (PMID 32456289, 2020). "First, in the current study, we excluded the subjects with liver dysfunction or liver cirrhosis, who might be with impaired parameters such as albumin, bilirubin and PT." (PMID 31615494, 2019). "Finally, we correlated plasma ARA, DHA, and ARA/DHA-ratio with serum albumin levels, as albumin has important immunomodulatory functions in patients with liver cirrhosis." (PMID 30703151, 2019). "An increased synthesis of prostaglandins appeared to be associated with decreased bacterial killing and contribute to immune paralysis of liver cirrhosis, which could be partially reverted by supplementation of human serum albumin." (PMID 30703151, 2019). "Whether long-term albumin infusions have a significant effect on morbidity and mortality in patients with advanced liver cirrhosis is currently being debated." (PMID 31717529, 2019). "However, presence of autoantibodies against albumin in patients with liver cirrhosis has been described." (PMID 30930689, 2019). "Univariate analysis showed that ineffective drainage was associated with the pre-ERCP serum total bilirubin level (P = 0.0075), pre-ERCP serum albumin level (P = 0.042), comorbid liver cirrhosis (P = 0.010), drained liver volume (P = 0.0010), and single stenting (P = 0.022)." (PMID 29963271, 2018). "Liver cirrhosis with the albumin serum levels higher than 2gr/dl was the second reason." (PMID 28979337, 2017). "Diagnostic accuracy was increased to an AUC of 0.826 (cut-off 1.29) for the detection of F4 (reference method liver biopsy), and an AUC of 0.832 (cut-off 1.29) for the detection of liver cirrhosis (reference method imaging) by adding total serum albumin to the model." (PMID 29072690, 2017).
liver cirrhosis (continued). "In addition, HBV-HCC patients were significantly more likely to have liver cirrhosis and Child class B disease, along with significantly lower serum ALB levels and platelet counts." (PMID 27495026, 2016). "Furthermore, age, platelet counts, prothrombin time, cholesterol amount, and albumin level were also relevant to liver cirrhosis (Stage 4)." (PMID 27363523, 2016). "According to the authors, decreased levels of serum nickel in liver cirrhosis may reflect diminished concentrations of serum nickeloplasmin and albumin." (PMID 27304961, 2016). "In addition, serum albumin concentration was recently shown to positively correlate with the regional cerebral blood flow in patients with liver cirrhosis." (PMID 25706868, 2015). "Furthermore, the albumin increment effect of GLN implicates its possible application in management of ascites related to albumin deficiency, such as liver cirrhosis." (PMID 24194753, 2013). "The relevant findings along with the laboratory investigations of patients is suspicious for pathologic changes in liver function as is expected in liver cirrhosis in a manner that blood bilirubin would be increased, while serum albumin and platelet count would be decreased." (PMID 23599716, 2013). "Therefore, to improve the postoperative medical and surgical outcomes in head and neck patients with liver cirrhosis, physicians should consider the potential role and serial changes of serum albumin level." (PMID 23285146, 2012). "Hemoglobin (β = 0.09 [SE = 0.04]), Albumin (β = 0.32[SE = 0.09]), Diastolic Blood Pressure (DBP) (β = 0.01[0.005) prior history of decompensation (β = 0.98[SE = 0.39] were significant factors associated with HRQOL in patients with liver cirrhosis." (PMID 22905795, 2012). "Hb (β = 0.09 [SE = 0.04]), Albumin (β = 0.32 [SE = 0.09]), diastolic blood pressure (DBP) (β = 0.01[0.005), and prior history of decompensation (β = 0.98[SE = 0.39] were found to be significant factors associated with liver cirrhosis." (PMID 22905795, 2012). "Second, detailed medical histories of each subject that might influence on serum albumin levels or protein intakes were unknown, such as nephrotic syndrome or liver cirrhosis." (PMID 20351474, 2010). "For patients with liver cirrhosis, albumin levels may generally be low due to hepatic dysfunction." (PMID 40400629, 2025). "In liver cirrhosis, albumin levels and the count of platelets may be diminished due to the liver’s impaired ability to synthesize albumin, together with the presence of hypersplenism, decreased thrombopoietin synthesis, and bone marrow suppression regarding platelets." (PMID 41301494, 2025). "However, the effects of rifaximin, a key drug in HE treatment, on the circulating albumin structure in patients with liver cirrhosis remain unclear." (PMID 36555935, 2022). "In liver cirrhosis, the original liver lobules are destroyed, forming false lobules, and the sinusoidal channels are disordered, which reduce the nutrient supply and oxygen supply of liver cells, aggravate the necrosis of liver cells, and reduce the synthesis of blood albumin by more than 50%." (PMID 35251204, 2022). "Interestingly, the levels of oxidized albumin correlated with progression of liver cirrhosis." (PMID 35740078, 2022). "Besides, patients with liver cirrhosis usually have significantly decreased serum albumin." (PMID 36212479, 2022). "Besides reviewing hallmarks of decompensated liver cirrhosis, we discuss alterations in albumin levels and molecular integrity and how this may affect the metabolism of the essential trace element zinc." (PMID 34836265, 2021). "However, compared to albumin, the available evidence is limited in patients with liver cirrhosis." (PMID 31717529, 2019). "Therefore, in conditions with altered albumin metabolism as liver cirrhosis, thyroid dysfunction, nephrotic syndrome with massive proteinuria, or inflammatory conditions, the use of GA may be misleading." (PMID 31891628, 2019).
liver cirrhosis (continued). "In chronic liver diseases, such as chronic hepatitis and liver cirrhosis, hypersplenism lowers the HbA1c values because of the shortened lifespan of the erythrocytes, whereas, it raises the GA values because of reduced albumin synthesis and the prolonged half-life of serum albumin." (PMID 25824109, 2015). "During hyper-metabolic states of albumin, such as nephrotic syndrome, hyperthyroidism, and glucocorticoid treatment, GA increases in relation to blood glucose, while it decreases in subjects with diminished albumin catabolism, including liver cirrhosis and hypothyroidism." (PMID 25265016, 2014). "We conducted the present analysis to evaluate how treatment adherence may affect the serum albumin level and prognosis in a prospective cohort of 5042 patients with liver cirrhosis who had started BCAA treatment at a fixed dose of three sachets/day in a preceding study." (PMID 23046471, 2013). "On multivariable linear regression, Hb (β = 0.09 [SE = 0.04]), Albumin (β = 0.32 [SE = 0.09]), diastolic blood pressure (DBP) (β = 0.01[0.005), and prior history of decompensation (β = 0.98[SE = 0.39] were found to be significant factors associated with CLDQ score in patients with liver cirrhosis." (PMID 22905795, 2012). "In conclusion, our results have shown that sodium, chlorides, albumin, MAP values, and the CAGIB score are reliable predictors of 7-day and 28-day nosocomial mortality in patients with liver cirrhosis and SIRS." (PMID 41226974, 2025). "The production of complement proteins, such as albumin, can be reduced in patients with HBV related liver cirrhosis." (PMID 39735192, 2024). "We investigated the Platelet-Albumin-Bilirubin (PALBI) score in comparison with the Child-Turcotte-Pugh (CTP) and MELD-Na (MELD-Na) scores in patients with liver cirrhosis." (PMID 39027759, 2024). "Cirrhosis of the liver is characterized by low serum levels of LDL, high-density lipoprotein (HDL) and albumin, and lipids carried in LDL and HDL are also reduced." (PMID 38256273, 2024). "Biochemical analysis showed that cirrhotic rats had a significant decrease in albumin levels and significantly elevated serum ALT, LDH, and ALP, similar to the biochemical alterations described in human liver cirrhosis." (PMID 37048049, 2023). "We found that ALB, TT, HCIPS, surgery, tumor number, tumor size, liver cirrhosis, BCLC stage, and TNM stage were related to the PFS (all P < 0.05)." (PMID 38041022, 2023). "In diseases such as liver cirrhosis and liver failure due to malabsorption of proteins, there is a reduction in DBP and albumin." (PMID 37005478, 2023). "The results of the univariate regression analysis indicate that night variables, including age, gender, AFP, PIVKA-II, AST, ALT, ALB, PT, and TP, were significant predictors of HCC when compared with HBV infection or liver cirrhosis." (PMID 37189543, 2023). "These facts suggest that the cut-off value of albumin of GPS (3.5 g/dL) is an unsatisfactory criterion for HCC patients whose basal diseases are often liver cirrhosis, and that ALBI grade should be used instead of albumin (3.5 g/dL) as a nutritional factor." (PMID 35326554, 2022). "Sex, increasing age, liver cirrhosis, an episode of ACLF, alcohol consumption, family history of HCC, TBil, albumin, AFP, platelet count, HBV DNA, ALT, and AST were introduced into the univariate Cox model." (PMID 36339647, 2022). "In patients with liver cirrhosis, BCAA over 1 year increased fat mass, plasma albumin, appetite, and physical function, but nutritional intake was not assessed." (PMID 34519439, 2021). "Of note, negative associations of serum PCSK9 with the MELD score, ALT, bilirubin, INR and CRP and positive correlations with albumin and leukocyte count existed in the HCV patients with liver cirrhosis." (PMID 33920491, 2021).